CX3CR1 (C-X3-C motif chemokine receptor 1)
Diseases named in the same sentence as CX3CR1 in open-access papers (continued):
Sharing a sentence is not in itself a finding about the gene and the disease.
tumor (continued). "Mechanistically, combined PD-1 and CX3CR1 blockade reduces the migration of tumor cells, decreases the abundance of immune suppressive myeloid cells in the tumor, increases mature macrophages in the tumor and reduces secretion of soluble mediators from the tumor." (PMID 37771579, 2023). "We hypothesized our mAb could inhibit migration of CX3CR1+ tumor cells towards a CX3CL1 gradient." (PMID 37771579, 2023). "However, it might also guide the CX3CR1-positive tumor cells out of the primary tumor towards pre-metastatic niches, for instance towards the bone marrow (bm)." (PMID 34070094, 2021). "Therefore, CX3CL1/CX3CR1-mediated signaling may be a new potential target for therapies that inhibit TAM recruitment into the tumor microenvironment." (PMID 34178692, 2021). "Consistent with a dependency on CX3CR1 for resolution of replication stress upon DNA crosslinks in platinum resistant cells via the FA pathway, FA pathway activation contributes to acquired cisplatin resistance and interfering with the FA pathway sensitizes tumor cells to cisplatin." (PMID 33810010, 2021). "Although neoantigen-specific CD8+ T cells and TILs were enriched in the CX3CR1+ subset in MC38 tumor-bearing mice treated with ICI therapy, it is possible that this subset also contains self-antigen reactive T cells that may have contributed to the increased clonality." (PMID 33658501, 2021). "Our lab has shown that the population of Cx3CR1+ monocytes/macrophages in the lungs increases in pre-metastatic tumor bearing mice, but not in mice injected with TF-deficient tumor cells or in mice that are anticoagulated with aspirin or hirudin during lung preconditioning." (PMID 33042789, 2020). "Moreover, compared to TAMs from WT tumor-bearing mice, those from Ubr5−/− tumor-bearing mice exhibited higher levels of M1 macrophage markers (e.g., il12a, Ccr2) and lower levels of M2 markers (e.g., Cx3cr1, il10)." (PMID 33293516, 2020). "However, the recruitment of microglia to a GBM tumor does not depend on the CX3CL1-CX3CR1 axis, although one study on the polymorphism of the CX3CR1 gene showed that the CX3CL1-CX3CR1 axis is important for the recruitment of tumor tissue by microglia." (PMID 32466280, 2020). "Furthermore, the high conservation between human and mouse CX3CR1 and the known cross-reactivity of mouse chemokine Cx3cl1 with the human receptor might account for the reduced extravasation of HPMo to tumours induced by the impairment of VEGF-A signalling." (PMID 29367702, 2018). "Due to the wide properties of CX3CR1, we can argue that the receptor downregulation caused by TGF-β1 in mature cytolytic NK cells might severely hamper their recruitment and functions at tumor sites." (PMID 28791023, 2017). "Therefore, we postulate that tumor-derived fractalkine release stimulates mobilization of CD11b+CX3CR1+ monocytes through fractalkine/CX3CR1 interaction, and these mobilized CD11b+CX3CR1+ monocytes in the PB have angiogenic and/or immunosuppressive activity in the tumor microenvironment." (PMID 29190915, 2017). "The recruitment of these MDSC subtypes to tumor sites is mediated by chemokines highly expressed by tumor-associated neutrophils, including CXCR2 and CXCR4, and chemokines over-expressed by tumor infiltrating macrophages, including CCR2, CCR5, CXCR4 and CX3CR1." (PMID 26462153, 2015). "However, there are also a small number of chemokine and GPCR interactions that may inhibit tumor cells invasion, such as CX3CR1/CX3CL1 interaction in glioma." (PMID 25110692, 2014). "However, precisely how CX3CR1 regulates TAMs subtypes in the tumor microenvironment remains unknown." (PMID 24245985, 2013). "We therefore wondered if CX3CR1 could play a role in tumor angiogenesis." (PMID 24245985, 2013). "Since CX3CR1 is expressed on the surface of macrophages and cross-talk between it and CX3CL1 have known roles in a diversity of tumor types, the CX3CL1-CX3CR1 axis may represent a novel regulator of tumor-associated macrophage recruitment." (PMID 23029290, 2012).
tumor (continued). "Thus, expression of CX3CR1 in tumor cells may serve as a predictor for the occurrence of brain metastases." (PMID 23029290, 2012). "CX3CR1+GPR56+ T cells express high levels of cytotoxic molecules and share TCR sequences with tumor-reactive-like T cells in tumors, and the degree of increase in the proportion of these cells is positively correlated with the PFS of patients." (PMID 41799205, 2026). "Some of these changes, including tumor reactive CD8+ T cells that express CD11, Granzyme B, and CX3CR1 and classical regulatory T cells, predicted clinical outcomes despite the limited number of patients in the study." (PMID 40082438, 2025). "These CDK inhibitors upregulate CX3CR1 expression via SMAD3 signaling, thereby promoting Mo-MDSC infiltration into tumors and facilitating immune evasion and tumor progression." (PMID 41316412, 2025). "CX3CR1 and PD1, recognized as markers of depleted macrophages closely involved in the pro‐tumor effects of M2‐TAMs, exhibited a discernible attenuation in the Vtnfl/fl S100a4‐Cre+ group." (PMID 40538300, 2025). "Mechanistically, dendritic cell clocks control expression of Cx3cl1, driving recruitment of CX3CR1+CD8+ T cells and thereby reshaping the tumor immune microenvironment to enhance immunotherapy efficacy." (PMID 41279119, 2025). "Neurons and tumor cells express CX3CL1, which interacts with CX3CR1 on microglia, promoting tumor cell invasion and microenvironment modulation." (PMID 41002423, 2025). "In terms of function, plasmacytoid DCs that produce IFNα stimulate the recruitment of CX3CR1+ MDSCs through hepatocyte IRF1/CX3CL1 signaling, subsequently promoting tumor recurrence following hepatectomy in HCC." (PMID 40470380, 2025). "A recent study demonstrated that CX3CR1+ PMN-MDSCs are markedly up-regulated in the intraperitoneal TIME following GC surgery, where they exhibit immunosuppressive activity and foster tumor progression." (PMID 41280721, 2025). "CX3CR1 plays dual roles: it facilitates recruitment of cytotoxic immune cells (e.g., NK and CD8 + T cells), but also enhances tumor cell survival and migration via pathways such as MAPK38,43." (PMID 40659866, 2025). "Our results demonstrated that the inhibition of CX3CR1 promoted M2 polarization of macrophages within the TME, while simultaneously augmenting the pro-tumor effects of M2-type TAMs on OS." (PMID 41267985, 2025). "For example, MMP9+ TAMs may play a role in tumor tissue remodeling, CX3CR1+ TAMs may exhibit unique phagocytic patterns, ECM-associated TAMs (ECMMac) involved in extracellular matrix remodeling are upregulated, and SPP1AREGMac exhibit distinct distribution within tumor tissues." (PMID 40191203, 2025). "To validate this observation, we employed flow cytometry to assess FABP7 expression in CLEC4F+ F4/80+ KCs and CX3CR1+ F4/80+ MoMFs from the liver PMN and MMN of MC38 tumor-bearing mice." (PMID 40765822, 2025). "Functionally, plasmacytoid DCs that produce IFNα stimulate the recruitment of CX3CR1+ MDSCs through hepatocyte IRF1/CX3CL1 signaling, resulting in tumor recurrence after hepatectomy in HCC." (PMID 40470380, 2025). "For example, recent studies have shown that inhibiting the CX3CL1‒CX3CR1 axis, particularly with drugs such as the Src inhibitor saracatinib, can block the chemotactic effect of CX3CL1 and reduce tumor metastasis in other cancers." (PMID 40051011, 2025). "We also observed increased expression of the activation/effector markers CD25, NKG2D, CX3CR1 and CD39 on the surface of CD8+ T cells in tumor, spleen, and blood following treatment with IL-2/JES6 alone or after ICIs." (PMID 40789741, 2025). "The mRNA expression of seven PRAN genes (CCL14, CPA3, CX3CR1, IKZF3, KIF21B, LINC00528, and SLC16A4) showed significant differences between normal and tumor samples in the advanced NSCLC cohort." (PMID 38728242, 2024).
tumor (continued). "Incubation of pNK cells with all three types of tumor spheroids led to a decrease in the surface expression of NKG2D to various degrees, in contrast to that of Tim-3 and CX3CR1." (PMID 39457710, 2024). "TAM subtypes interact with different PitNET lineages; CX3CR1+ TAMs interact with NR5A1+ tumor cells through the INHBA-ACVR1B axis, promoting tumor cell apoptosis." (PMID 38658971, 2024). "The potential mechanism by which CX3CR1 influences CD14+ CD16− monocytes to facilitate the progression of PCa is through activation of the CX3CR1/CX3CL1 signalling pathway, promoting tumour angiogenesis, migration, and invasion." (PMID 39098992, 2024). "We found that GZMA expression was higher in CX3CR1+ CD8+ T cells compared to CX3CR1− CD8+ T cells in both spleen and the tumor while expression of GZMB was equivalent." (PMID 38881188, 2024). "To assess the transcriptomic signatures of CX3CR1+ CD8+ T cells in the tumor microenvironment, we analyzed the scRNA-seq dataset (GSE120575), where 48 tumor samples were collected at baseline and/or during ICI therapy from 32 patients." (PMID 38881188, 2024). "Our data revealed that tumor antigen–specific CX3CR1− CD8+ T cells can fully differentiate outside the secondary lymphoid organs and generate CX3CR1+ CD8+ T cells in the tumor microenvironment." (PMID 38881188, 2024). "We found CX3CR1+ PMN-MDSCs and TAMs in ILF, but these tumor-promoting cells reportedly interact with each other, as MDSCs promote TAM differentiation, and interaction can differentiate PMN-MDSCs and M-MDSCs." (PMID 38433196, 2024). "Collectively, these data support the notion that CX3CR1+ CD8+ T cells differentiate directly from intratumoral CX3CR1− CD8+ T cells and that T-cell differentiation occurs within the tumor microenvironment." (PMID 38881188, 2024). "To exclude the possibility of off-target effects of the Cx3cr1-Cre strain on the status of PHGDH in T cells, we evaluated PHGDH protein expression in T cells within tumor tissues via immunofluorescence staining of CD3." (PMID 38409249, 2024). "Among these are CX3CR1 and CXCR3, which play pivotal roles in the homing of NK cells to peripheral tissues, including tumor sites." (PMID 39563446, 2024). "By contrast, highly expressed genes in cluster I10 included multiple known pro-tumor markers in macrophages, such as TREM2, CX3CR1, and SPP1." (PMID 38167466, 2024). "We observed increased colocalization of CX3CR1+ cells and PDPN+ structures with increasing lymph-circulating tumor cells after CX3CL1 overexpression." (PMID 38775151, 2024). "We highlight CX3CR1 modulation and/or chemokine remodelling of OAC tumour as two promising approaches to redirect NK cell migration away from OAC omentum and towards the tumour." (PMID 38369570, 2024). "CX3CR1 upregulation correlated with poor prognosis due to the increased survival of angiogenic macrophages in the TME, which contributed to tumor metastasis." (PMID 38731899, 2024). "CX3CR1 activates several signaling pathways, such as MAPK and AKT that are involved in tumor biology." (PMID 39594776, 2024). "INHBA-ACVR1B was found to be the top-ranked ligand-receptor pair among CX3CR1+ macrophages and NR5A1+ tumor cells interaction." (PMID 38658971, 2024). "Therefore, FKN/CX3CR1 may be a favorable or unfavorable prognostic factor, with evidence for anti-tumor functions primarily coming from prognostic studies, while evidence for pro-tumor function tends to be from tumor development studies." (PMID 38731899, 2024). "A combination of the CX3CR1 inhibitor with veliparib was strongly synergistic in reducing clone formation in OVCAR-4 and reducing tumor burden in OVCAR-4/athymic nude mouse xenograft experiments." (PMID 39594684, 2024). "The mRNA expression of seven PRAN genes (CCL14, CPA3, CX3CR1, IKZF3, KIF21B, LINC00528, and SLC16A4) exhibited noticeable difference between normal and tumor in NSCLC." (PMID 38728242, 2024).
tumor (continued). "In this study, we focused our investigation on the CCR1, CX3CR1, and CCR5 chemokine pathways, which have important roles in anti-tumour T cell biology." (PMID 38672174, 2024). "The difficulty is that the effect of FKN on the functioning of the immune system in the TME is complex and depends on the type of cancer and the heterogeneity of a specific tumor, which affects the expression of FKN and CX3CR1 in cells." (PMID 38731899, 2024). "The results demonstrated that CX3CR1+, C1Q+, and GPNMB+ macrophages exhibited the highest interaction with NR5A1+, TBX19+, and POU1F1+ tumor cells, respectively." (PMID 38658971, 2024). "Instead, CCR6 alone was as efficient or even more efficient in directing T cells into the tumor as was dual transduction with CCR6 and CXCR1 or CCR6 and CX3CR1." (PMID 37301772, 2023). "One important factor is CX3CL1 as myeloid cells have been shown to have high expression of CX3CR1 and traffic towards a CX3CL1 gradient found in the tumor microenvironment." (PMID 37771579, 2023). "We treated the CT26 tumor cell line with inflammatory cytokines IFN-γ and TNF-α for 24 hours and observed a 1.3-1.5-fold increase in the MFI of CX3CR1 expression compared with untreated cells." (PMID 37771579, 2023). "We tested the expression of CX3CR1 in mouse tumor cell line CT26 in vitro and in ex vivo CT26 tumor harvests from tumor bearing mice and observed high expression of CX3CR1 in the tumor cells in vitro and ex vivo." (PMID 37771579, 2023). "CX3CL1, as a prognosis indicator, promoted tumour cell migration, invasion and ICAM‐1 expression by activating CX3CR1/PLCβ/PKCα/c‐Src/c‐Jun/AP‐1 pathway." (PMID 37082943, 2023). "This axis of CX3CR1 with its ligand Fractalkine CX3CL1 is suggested to play an ambiguous role in oncogenesis since it can exercise pro- and anti-tumor functions." (PMID 36900266, 2023). "Here, we test a novel CX3CR1 monoclonal antibody that blocks the CX3CL1-CX3CR1 interaction and promotes responses to anti-PD-1 immunotherapy in a mouse tumor model." (PMID 37771579, 2023). "Treatment with CX3CR1 mAb also resulted in a reduction of NLRP3 mRNA, a component of the tumor inflammasome." (PMID 37771579, 2023). "We confirmed that CD11b+ myeloid cells in the CT26 tumor express a high percentage and MFI of CX3CR1 but those in the spleen had low expression consistent with previous studies." (PMID 37771579, 2023). "Since that time, the CX3CR1+ CD8 T cell population has been found to increase in responders after treatment in a number of studies, including models of both tumor and chronic viral infection." (PMID 36656137, 2023). "The current findings have indicated that increased CX3CR1 levels, both in bladder tissue and peripheral blood samples, mirrored dynamic fluctuations observed in CD8+ TILs within the tumor microenvironment after OncoTherad® (MRB-CFI-1) treatment application." (PMID 38139364, 2023). "For primary tumor progression, CX3CL1/CX3CR1 played an important role in modulating inflammatory responses associated with macrophage survival and monocyte homeostasis." (PMID 35478937, 2022). "CX3CR1 was positively correlated with immune and ESTIMATE scores and negatively correlated with tumor purity." (PMID 36091132, 2022). "CX3CR1 and its ligand CX3CL1 play both a role in activating anti-tumor immunity and in promoting tumor formation and progression." (PMID 35223493, 2022). "ADRB2, ANGPTL4, BDNF, CBLC, CX3CR1, and IL3RA were found markedly different expression between the tumor and normal group." (PMID 35833114, 2022). "To further verify the expression of CX3CR1 and the potential functional role of CX3CR1 in CRC, we enrolled a total of 60 patients with CRC and analyzed the mRNA and protein expressions of CX3CR1 in the tumor tissues." (PMID 35140706, 2021). "Although the exhausted CD8+ T cells have been the majority of the tumor-infiltrating CD8+ T cells, CX3CR1-and granzyme K (GZMK)-expressing CD8+ T cells have also been identified." (PMID 34947886, 2021).
tumor (continued). "CX3CR1-KD or/and LFA-1-KD treatments also downregulated the aggressive propensity of tumor cells, as evidenced by reduced levels of phosphorylated PI3K and AKT, and decreased levels of MMP-2, compared with controls." (PMID 33754027, 2021). "Our previous findings have demonstrated that IL-21-producing CD4+ T cell ACT augments the effector CX3CR1+ CD8+ TIL population, resulting in enhanced tumor control." (PMID 33809259, 2021). "First, we assessed the frequency of Tet+ CD8+ T cells within the PB CX3CR1+ and CX3CR1− subsets in MC38 and CT26 tumor-bearing mice." (PMID 33658501, 2021). "Markedly improved tumor control and survival with increased frequency of CX3CR1+ CD8+ T cells were observed in MC38 and CT26 tumor-bearing mice treated with ICI compared to mice receiving isotype Ab." (PMID 33658501, 2021). "CX3CR1 and CSF1R are highly expressed in FCGR3A+ (CD16+) subset, which can be identified as an inflammatory phenotype in anti-tumor immune response." (PMID 33648605, 2021). "CX3CR1 was decreased in CRAD tissues and cell lines and was related to T and N stages, tumor differentiation, and prognosis." (PMID 35140706, 2021). "Pharmacological blockade of HIF using digoxin or antibody inhibition of CX3CR1 have been demonstrated to suppress MDSC recruitment, angiogenesis, and tumor growth." (PMID 33422072, 2021). "Successful treatment of tumor-bearing mice with ICI increases the frequency and T-cell receptor clonality of the peripheral CX3CR1+CD8+ T-cell subset that includes an enriched repertoire of tumor-specific and tumor-infiltrating CD8+ T cells." (PMID 33658501, 2021). "It is reported that the expression levels of CX3CR1, CXCR4, CXCR5, and CCR7 in tumor tissues are significantly increased, which is able to affect the survival time of patients." (PMID 34603645, 2021). "We investigate the frequency of CX3CR1+ CD8+ T cells in PB before and during ICI therapy, and delineate the TCR repertoire in peripheral CX3CR1+ CD8+ T-cell subsets and CD8+ tumor-infiltrating lymphocytes (TILs) using preclinical models." (PMID 33658501, 2021). "More recently, our findings suggest that IL-21-producing CD4+ T cells are required for the formation of effector CX3CR1+ CD8+ TILs, which enhances tumor control." (PMID 33809259, 2021). "Upon assessment of tumor-reactive CD8+ T cells, we found that the Batf−/− group had a significantly lower frequency of effector CX3CR1+ CD8+ T cells with a concomitant increase in Ly108− CX3CR1− exhausted CD8+ T cells." (PMID 33809259, 2021). "Expression of membrane receptors such as FCGR3A and CX3CR1, and cytotoxic genes like GZMB, FGFBP2, PRF1, and GNLY increased gradually during this transition, implying a gradually acquired tumor-killing ability in CD56dim NK cells." (PMID 33298893, 2020). "Among these genes, CX3CR1 and UBD can promote tumor metastasis and the epithelial to mesenchymal transition." (PMID 32208363, 2020). "Their migration to inflamed tissues including tumor sites involves a series of chemokine receptors such as CCL3-5/CCR5, CXCL10/CXCR3, and CX3CL1/CX3CR1." (PMID 31991604, 2020). "For example, IL-15 stimulates migration of CD56bright NK cells to the tumor site by increasing the expression of CCR5, while inhibiting trafficking of CD56dim counterparts by decreasing CXCR4 and CX3CR1 expression." (PMID 33260925, 2020). "To understand the effects of sGRP78 on the motility of hepatic myeloid DCs and macrophages within the tumor microenvironment, we performed intravital imaging using C57BL/6 CX3CR1-GFP mice." (PMID 33133103, 2020). "CD8A, DOK2, CX3CR1, TYROBP, CXCL9, CD300LF, and IFNG were identified as significant DEGs between tumor samples with high and low CD200R1 expression." (PMID 32635224, 2020). "The CXCR3 and CX3CR1 chemokine receptor ligands CXCL9-11 and CX3CL1, respectively, are mainly responsible for the tumor-suppressive lymphocytic infiltration into the tumor micromilieu." (PMID 31482487, 2019).